IL18 (interleukin 18)
Diseases named in the same sentence as IL18 in open-access papers (continued):
Sharing a sentence is not in itself a finding about the gene and the disease.
metabolic syndrome (115 papers, 2008 to 2026). A cluster of metabolic risk factors for CARDIOVASCULAR DISEASES and TYPE 2 DIABETES MELLITUS. "IL-18 is a pro-inflammatory cytokine belonging to the IL-1 superfamily, closely associated with metabolic syndrome and an important predictor of long-term cardiovascular mortality." (PMID 41490440, 2026). "Higher levels of IL-18 have been observed in men with metabolic syndrome and associated with vascular events in patients with angina or congenital heart disease." (PMID 39940942, 2025). "In a regression model adjusted with treatment for dyslipidemia, elevated level of IL-18 was also associated with stable disease." (PMID 39068298, 2024). "High serum levels of IL18 increase the risk of metabolic syndrome characteristics such as hypertriglyceridemia, and are also linked to serum triglyceride levels." (PMID 38139000, 2023). "IL-18 deficiency caused dyslipidemia and steatosis, while the administration of a recombinant IL-18 reverted this process." (PMID 36768637, 2023). "Intriguingly, our study reports decreased levels of several pro-inflammatory cytokines in NASH that have been associated with the metabolic syndrome, such as IL-6 and IL-18." (PMID 37342340, 2023). "Interleukin-18 (IL-18) is a proinflammatory cytokine associated with metabolic syndrome (MS), of which is often considered as a feature of NAFLD." (PMID 36267567, 2022). "Some studies evidence that circulating increased IL-18 associates with obese subjects and metabolic syndrome." (PMID 31548850, 2019). "In this section, we will discuss the beneficial roles of IL-18 in metabolic homeostasis and introduce topics regarding the unique pathogenic action of IL-18 in the development of metabolic syndrome." (PMID 30717382, 2019). "The fact that mice deficient in IL-18 develop a metabolic syndrome-like phenotype is consistent with a role for IL-18 in homeostasis." (PMID 24115947, 2013). "Reduction in serum IL-18 levels across increasing numbers of +183 G-alleles (rs 5744292) is especially apparent in patient with diabetes type 2 and metabolic syndrome, suggesting a beneficial GG genotype in relation to cardiovascular outcome in these patients." (PMID 23039238, 2012). "We aimed to investigate how lean body mass is related to circulating Interleukin 18 (IL-18) and its association with metabolic syndrome (MetS) among apparently healthy Chinese." (PMID 21437204, 2011). "We investigated the effect of IL18 variants on intermediate phenotypes of the metabolic syndrome in each of the three studies." (PMID 20227263, 2011). "The reduction in serum IL-18 levels across increasing numbers of +183G-alleles was especially apparent in patient with diabetes type 2 and metabolic syndrome, suggesting a beneficial GG genotype in relation to cardiovascular outcome in these patients." (PMID 22141572, 2011). "In a post hoc analysis from the same trial, the reduction of IL-18 levels was associated with an increased number of metabolic syndrome components that improved during three years of intervention." (PMID 20331890, 2010). "The purpose of this review is to outline the role of IL-18 in the metabolic syndrome, with particular emphasis on cardiovascular risk and the potential effect of life style interventions." (PMID 20331890, 2010). "The purpose of this review is to outline the role of IL-18 in the metabolic syndrome, with particular emphasis on CVD risk and life style interventions." (PMID 20331890, 2010). "Therefore, we evaluated two IL-18 SNPs (rs3882891C/A; NC_000011.10:112144037:C:A and rs1946518A/C; NC_000011.10:112164734:A:C) as candidate biomarkers for susceptibility to dyslipidemia." (PMID 38774744, 2024). "However, the association between these two IL-18 genetic polymorphism and dyslipidemia, which is the major cause of CAD, is rarely defined." (PMID 38774744, 2024).
metabolic syndrome (continued). "One wonders whether single nucleotide variant of the human NLRP1 gene correlates with IL-18 levels and consequently with the susceptibility of obese individuals to develop dyslipidemias and/or T2D." (PMID 31554824, 2019). "Interleukin-18 (IL-18) is a proinflammatory cytokine associated with metabolic syndrome (MS)." (PMID 29854715, 2018). "In addition, IL-18 deficiency or IL-18 receptor deficiency results in the development of a metabolic syndrome in mice." (PMID 24115947, 2013). "Besides, the +183 A/G polymorphism at the 3’-untranslated region of interleukin (IL)-18 genes is associated with the circulating IL-18 levels, especially apparent in patients with type 2 DM and metabolic syndrome." (PMID 23216712, 2012). "The effect of variants on IL-18 levels and their association with insulin levels and sensitivity suggests that insulin sensitivity and metabolic syndrome may have a genetic basis." (PMID 20227263, 2011). "A recent study of non-diabetic Caucasians reported the association of promoter variant, +183A > G (rs5744292), which is in complete LD with rs1946519 and rs3882891, with increased levels of serum IL-18, increased risk of metabolic syndrome and impaired insulin sensitivity." (PMID 20227263, 2011). "The metabolic syndrome is thought to be associated with a chronic low-grade inflammation, and a growing body of evidence suggests that interleukin-18 (IL-18) might be closely related to the metabolic syndrome and its consequences." (PMID 20331890, 2010). "However, we recently showed that arterial stiffness measured by brachial pulse wave propagation was associated with IL-18 levels and components of the metabolic syndrome, even in multivariate analyses, both cross sectionally and during three years follow up." (PMID 20331890, 2010). "Moreover, in a middle aged cohort of men with the metabolic syndrome, we have reported reduced levels of IL-18 associated with improvement of metabolic syndrome components by a combined intervention consisting of aerobic exercise and strength training." (PMID 20331890, 2010). "However, a growing body of evidence suggests that IL-18 is closely associated with the metabolic syndrome and its consequences." (PMID 20331890, 2010). "The metabolic syndrome is associated with the occurrence of chronic inflammation that remains at a low level, which is characterised by the predominance of pro-inflammatory factors in the systemic circulation, e.g., IL-6 and TNFα and IL-18, which are involved in the pathogenesis of LUTS/BPH." (PMID 37847180, 2023). "IL-18 may have a causal role in maintaining the lipid concentration and may be a promising factor contributing to the development of novel treatment options for dyslipidemia through improving energy imbalance by lipids in BAT." (PMID 30453990, 2018). "AT levels of IL-18 have been found to be correlated with BMI, and serum IL-18 is significantly higher in people with T2D and metabolic syndrome." (PMID 39064738, 2024). "In the FACT cohort, multivariable logistic regressions adjusted for atrial fibrillation, history of smoking, rheumatic disease and treatment for dyslipidemia, elevated levels of IL-17 (p = 0.007) and IL-18 (p = 0.003) were predictors of ACS." (PMID 39068298, 2024). "IL-18 plays a major role in the induction of interferon-gamma signaling, and an increase in circulating IL-18 has been demonstrated in numerous inflammatory disease states including metabolic syndromes, psoriasis, and IBD." (PMID 37170273, 2023). "While it shows beneficial effects in dyslipidemia and steatosis, IL-18 seems to participate in fibrogenesis." (PMID 36768637, 2023). "A 43% decrease in IL-18 levels after aerobic exercise training in inactive men and women with metabolic syndrome and a 20% decrease in IL-18 mRNA in adipose tissue after exercise training in obese individuals have been demonstrated." (PMID 37446334, 2023).
metabolic syndrome (continued). "IL-18 has been shown to participate in processes involved in inflammaging, and increased levels of IL-18 have been reported in individuals with metabolic syndrome." (PMID 37569647, 2023). "This phenotype was attributed to IL-18 production since IL-18 is increased in WAT of obese NLPR1-null mice and IL-18-deficient mice also develop metabolic syndrome." (PMID 36175539, 2023). "Nevertheless, the direct molecular role of IL18 in dyslipidemia, NAFLD, and NASH remains to be clarified." (PMID 38139000, 2023). "Plasma levels of IL-6 and IL-18 were significantly higher in our group of patients with dyslipidemia and confirmed the presence of unstable atherosclerotic plaque compared to in the healthy control group." (PMID 35630041, 2022). "It was revealed that in Wistar rats with metabolic syndrome, intravenous administration of IL-18 resulted in the activation of monocyte recruitment into the aortic wall." (PMID 36138973, 2022). "The intravenous administration of IL-18 significantly improved dyslipidemia, inhibited body weight gain, and prevented the onset of NASH in these mice." (PMID 36289606, 2022). "Circulating IL-18 levels correlate with metabolic syndrome, but, on the other hand, it has been also demonstrated that IL-18 production negatively regulates NASH progression via modulation of the gut microbiota." (PMID 34957156, 2021). "The elevated serum IL-18 levels in type 2 DM and metabolic syndrome have been reported and have been suggested to contribute to microangiopathy in type 2 DM in recent studies." (PMID 32053656, 2020). "The degree of cardiorespiratory fitness in metabolic syndrome subjects has been shown to have inverse associations with CRP, IL-6, and IL-18, partially explained by the degree of abdominal obesity." (PMID 31331009, 2019). "Our results indicate that the Nlrp1b1 inflammasome promotes interleukin 18 (IL-18) maturation in the adipose tissue, resulting in lipolysis and reduced dyslipidemia in obese mice." (PMID 31554824, 2019). "Patients with metabolic syndrome have elevated circulating levels of IL-18, a product of NLRP3 inflammasome activation." (PMID 30717382, 2019). "In concordance with the IL-18 levels, both Balb/c and Nlrp1b1-transgenic mice showed reduced hepatic steatosis and reduced dyslipidemia when fed with the HFD than obese Wt C57BL/6 mice." (PMID 31554824, 2019). "Together, our results indicate that the Nlrp1b1 inflammasome has a protective function against developing dyslipidemia and T2D in response to energy excess, through efficient IL-18 production." (PMID 31554824, 2019). "Intravenous administration of recombinant IL-18 (rIL-18) for Il18−/− mice significantly improved dyslipidemia and prevented the onset of NASH." (PMID 29514661, 2018). "Although protein expression in BAs from Il18−/− mice, which was significantly different such as UCP1, was not affected by rIL-18 administration, in Il18−/− mice, dyslipidemia was improved by short-term (2 weeks) rIL-18 administration." (PMID 30453990, 2018). "Previously published studies demonstrated elevated circulating levels of IL-18 in adult patients with metabolic syndrome and its components." (PMID 29854715, 2018). "We have previously investigated the potential pathophysiological relationship between IL-18 and dyslipidemia, non-alcoholic fatty liver disease and non-alcoholic steatohepatitis, which were mediated by lipid energy imbalance." (PMID 30453990, 2018). "In contrast to IL-1, however, IL-18 protects against metabolic syndrome, although patients with the metabolic syndrome show increased serum levels of IL-18." (PMID 26549942, 2015). "Subsequently, Caspase-1 inhibition by quercetin and allopurinol prevented kidney IL-1β and IL-18 release and over-production triggered by hyperuricemia and dyslipidemia in this model." (PMID 22701621, 2012). "Mounting evidence suggests that IL-18 is involved in the pathogenesis of obstertrical disease and metabolic syndrome." (PMID 21244650, 2011).
metabolic syndrome (continued). "In a large cohort consisting of men and women with known coronary artery disease, IL-18 was the only independent predictor of cardiovascular mortality in a subgroup with the metabolic syndrome, even after adjustment for CRP, IL-6 and fibrinogen." (PMID 20331890, 2010). "Interestingly, a recent study showed that one such polymorphism was associated with increased serum levels of IL-18, impaired insulin sensitivity and increased risk of having the metabolic syndrome, suggesting that IL-18 might be involved in the pathogenesis of the syndrome." (PMID 20331890, 2010). "To date, only two studies have prospectively evaluated IL-18 as a potential predictor of cardiovascular events in populations with the metabolic syndrome." (PMID 20331890, 2010). "Further research will be required to more accurately elucidate the function of Angptl4, but also of Il18, Fgf15, Mif and Igfbp3 in the small intestine and their possible role in the etiology of the metabolic syndrome." (PMID 18457598, 2008). "Alternatively, IL‐18 production during metabolic syndrome may be regulated by different upstream pathways." (PMID 39327931, 2025). "Indeed, a protective role for NLRP1‐dependent IL‐18 has been demonstrated during adiposity and metabolic syndrome." (PMID 39327931, 2025). "Cross-sectional studies also indicate that this adipokine is crucial in the pathogenesis of the metabolic syndrome and suggest that chemerin, IL-18, and adiponectin may reciprocally participate in its development." (PMID 39940942, 2025). "Previous study shows that deletion of IL-18 develops dyslipidemia in mice." (PMID 38774744, 2024). "Furthermore, 8-week high-intensity and aerobic interval training (three times/week) in men and women with metabolic syndrome resulted in decreased IL-18 mRNA levels in abdominal AT and a numerical decrease in plasma IL-18 concentration." (PMID 38681198, 2024). "Additionally, Il18−/− mice with dyslipidemia, NAFLD, and NASH showed inhibition of the Wnt signaling pathway, reduced expression of cyclin D1 (Ccnd1), and disturbances in the circadian rhythm." (PMID 38139000, 2023). "Additionally, IL-18 has been shown to be upregulated in individuals with the metabolic syndrome, with its circulating levels raising as the components of the syndrome increase." (PMID 37049621, 2023). "In addition, the authors showed that an increase in the expression of IL-18 in the aorta in rats with metabolic syndrome leads to an increase in insulin resistance (IR) due to the activation of the proinflammatory NF-κB signaling pathway." (PMID 36138973, 2022). "Yamanishi and colleagues showed that IL-18 knockout mice developed dyslipidemia resulting in NASH." (PMID 36289606, 2022). "IL-18 is a marker of hepatic steatosis and regulate the process of metabolic syndrome in NASH." (PMID 34321090, 2021). "Elevated serum IL-18 levels were reported in patients with metabolic syndrome and type 2 DM." (PMID 32053656, 2020). "We have also previously found that Il18−/− mice developed dyslipidemia, NAFLD and NASH." (PMID 30453990, 2018). "In addition, our previous study has revealed that Il18−/− mice showed dyslipidemia, resulting in NAFLD and steatohepatitis." (PMID 30453990, 2018). "The proinflammatory cytokine IL‐18 is involved in the pathogenesis of metabolic syndrome." (PMID 28508444, 2017). "IL-18 has also been reported to be involved in metabolic syndrome." (PMID 26549942, 2015). "Adipocytes from obese individuals produce higher levels of IL-18 compared to lean individuals and higher circulating IL-18 levels were observed in obese individuals, and those with Type 2 Diabetes (T2D) and the metabolic syndrome." (PMID 20227263, 2011). "In another study, we showed that the reduction of IL-18 levels by exercise was significantly associated with improvement of the metabolic syndrome, but not with a reduction in visceral fat." (PMID 20331890, 2010).
metabolic syndrome (continued). "Furthermore, IL-18 has been shown to be elevated in subjects with the metabolic syndrome and to increase in parallell with an increasing number of components of the syndrome." (PMID 20331890, 2010). "Furthermore, we showed a tendency to additive effect of exercise and pravastatin on serum levels of IL-18 in subjects with the metabolic syndrome." (PMID 20331890, 2010). "Moreover, Mediterranean-like diet was shown to reduce levels of CRP, IL-6 and IL-18 in a middle-aged population with the metabolic syndrome." (PMID 20331890, 2010). "IL‐18 is a proinflammatory cytokine that plays a key role in promoting immune responses by inducing interferon‐gamma (IFN‐γ) production, and it is implicated in inflammation‐driven diseases, including autoimmune disorders, metabolic syndromes, and chronic inflammatory conditions." (PMID 40317574, 2025). "IL-18 may be related to metabolic syndrome and its consequences, that is, it may be involved in the set of risk factors that identify a population at increased risk for developing metabolic syndrome, which encompasses type 2 diabetes and cardiovascular diseases." (PMID 36816031, 2023). "In an STZ-induced rat model of diabetic nephropathy (DN) with hyperuricemia and dyslipidemia, overexpression of NLRP3 inflammasome components [apoptosis-associated speck-like protein (ASC) and caspase-1] has been found to be associated with elevated IL-1β and IL-18 levels." (PMID 34267672, 2021). "Therefore, it seems possible that the IL-18 effect on BMI and metabolic syndrome may result through two distinct pathways." (PMID 20227263, 2011). "High baseline IL-18bp, as seen in metabolic syndrome conditions, may prevent a sufficient rise in fIL-18 necessary to facilitate a strong Th1 response for early antigen-control, resulting in antigen escape from symptom day 15 onwards, and persistent inflammasome-mediated IL-18 release." (PMID 36823262, 2023). "In metabolic syndrome, MCP-1, IL-18, and IL-1B are elevated and stimulate pro-inflammatory actions of tissue neutrophils and macrophages in vascular endothelial and smooth muscle cells." (PMID 36012132, 2022). "For instance, IL-18, the designated marker of NLRP3 inflammasome activation status was decreased by 43% in men and women with metabolic syndrome in response to a 12-week aerobic interval training program (three times a week)." (PMID 35273516, 2022). "We have previously shown that IL-18 administration not only remarkably improved dyslipidemia, NAFLD and NASH in Il18−/− mice, but it also inhibited body weight gain in Il18+/+ mice." (PMID 30453990, 2018). "Despite IL-18 not being a routine biomarker for clinical diagnosis, its role in the inflammation driving metabolic syndrome suggests potential implications for understanding and treating the condition." (PMID 40277935, 2025). "The dyslipidemia, NAFLD, and NASH in Il18−/− mice were improved by administration of rIL18." (PMID 38139000, 2023). "In addition, exogenous administration of IL-18 counteracts steatohepatitis in mice upon HFD, further highlighting the importance of NLRP1-IL-18 signaling in controlling metabolic syndromes." (PMID 30319645, 2018). "Both IL-18 and IFN-γ are cytokines that have been shown to be related to the metabolic syndrome." (PMID 29590212, 2018). "We found that short-term intravascular administration of IL-18 (2 weeks) induced no kidney damage, and appeared to improve dyslipidemia in Il18−/− mice." (PMID 29514661, 2018). "IL-18-knockout (Il18−/−) mice also showed dyslipidemia, non-alcoholic fatty liver disease (NAFLD), or non-alcoholic steatohepatitis (NASH)." (PMID 29514661, 2018). "IL-18 levels were significantly higher in men as compared to women, and in patients with diabetes type 2 and metabolic syndrome compared to those without (p ≤ 0.001, all)." (PMID 22141572, 2011).